ABCC1 (ATP binding cassette subfamily C member 1 (ABCC1 blood group))
Diseases named in the same sentence as ABCC1 in open-access papers (continued):
Sharing a sentence is not in itself a finding about the gene and the disease.
glioma (continued). "In glioma, the most relevant ABC transporter proteins are p-glycoprotein (ABCB1), MDR-associated protein-1 (ABCC1), and breast cancer resistance protein (ABCG2)." (PMID 30123112, 2018). "Although ABCC1 is overexpressed in high-grade gliomas and is associated with multidrug resistance in cancer cells, the inhibition of ABCC1 has not led to TMZ sensitization in GBM." (PMID 37175636, 2023). "Then, we explored ABCC1 gene expression in human glioma tumor tissues." (PMID 35803910, 2022). "Recurrent glioma patients with higher ABCC1 also presented decreased OS." (PMID 35803910, 2022). "Once we demonstrated that NRF2 has a positive correlation with ABCC1 expression in vitro, we next investigated whether the expression of those genes would present a similar pattern in glioma patients." (PMID 35803910, 2022). "Likewise, high grade glioma cases (according to WHO classification) displayed increased levels of ABCC1." (PMID 35803910, 2022). "Notably, we found a positive correlation between NRF2 and ABCC1 gene expression in three cohorts of glioma patients (CGGA, TCGA, and REMBRANDT)." (PMID 35803910, 2022). "Also, ABCC1 gene expression is an independent prognostic factor in glioma patients, corroborating the need for a more effective treatment for this group of patients." (PMID 35803910, 2022). "This suggested that miR-9-5p could enhance the sensitivity of TMZ-resistant glioma to TMZ through ABCC1." (PMID 34532283, 2021). "In the early studies, it was shown that ABCC1 played a sensitization role in TMZ-resistant glioma cells, revealing that miR-9-5p may adjust the resistance of glioma to TMZ through ABCC1." (PMID 34532283, 2021). "miR-9-5p decreased in glioma patients, and by restoring the content of miR-9-5p, ABCC1 could be inhibited to promote the sensitivity of TMZ-resistant glioma cells to TMZ, which may be a potential therapeutic target in clinic." (PMID 34532283, 2021). "We can conclude that miR-9-5p could act in the mechanism of drug resistance of glioma cells to TMZ by regulating ABCC1." (PMID 34532283, 2021). "Thus, we identified the LINC00470/miR‐134/MYC/ABCC1 axis and illuminated its biological role and mechanism in glioma." (PMID 32916774, 2020). "Our results provide a new understanding of the role and mechanism of the LINC00470/miR‐134/MYC/ABCC1 axis in glioma, which may contribute to the development of novel therapeutic targets and improve the chemosensitivity of glioma." (PMID 32916774, 2020). "That is, LINC00470, miR‐134, MYC and ABCC1 can form a new regulatory axis in gliomas." (PMID 32916774, 2020). "ABCC1 has been shown to regulate chemoresistance in glioma, breast, prostate, and liver cancers." (PMID 29643985, 2018). "Therefore, ABCC1 in tumor tissues of glioma patients was also tested." (PMID 34532283, 2021). "In this study we aimed to investigate the role of SeNPs and 0.2% Cs-SeNPs on the expression levels of genes involved in drug resistance in glioma, including MRP1 (ABCC1) and BRCP (ABCG2), which can predict clinical progression." (PMID 35957037, 2022). "In conclusion, miR-9-5p was low in glioma, and elevation of miR-9-5p can increase the sensitivity of glioma to TMZ through ABCC1, which is a potential therapeutic target." (PMID 34532283, 2021). "We can confirm that increase of miR-9-5p hindered ABCC1 and increased the sensitivity of TMZ-resistant glioma cells to TMZ, thus inhibiting cell activity and inducing apoptosis." (PMID 34532283, 2021). "Although we identified the role of LINC00470 and miR‐134 in glioma and established the LINC00470/miR‐134/MYC/ABCC1 axis, certain limitations out of our study remain and should be improved upon in the future." (PMID 32916774, 2020). "We investigated levels of multiple drug resistance-related genes in U87 and primary glioma cells, including genes related to drug efflux (ABCB1, ABCC1, ABCC2, ABCC4, ABCG2, ATM), DNA damage repair (MGMT) and stemness (CD133)." (PMID 27486877, 2016).
glioma (continued). "Before drug treatments, the expression ratios of drug-resistant ABC transporters in glioma cells (ABCB1 = 0.50 ± 0.06, ABCC1 = 0.26 ± 0.10, and ABCG2 = 0.57 ± 0.01) were evidently lower than those in GSCs (ABCB1, ABCC1 or ABCG2 = 1, respectively)." (PMID 25153726, 2014). "This study established a co-expression relationship between MYC and ABCC1, and that overexpression of MYC could increase ABCC1 levels in glioma cells." (PMID 39403602, 2024). "Likewise, the ABC transporters, MRP1 (ABCC1), MRP3 (ABCC3), and MRP4 (ABCC4), are highly expressed in glioma cells." (PMID 35740330, 2022). "The first member of this group, ABCC1 (also called MRP-1), has garnered a high degree of interest due to its dysregulation in many forms of cancer including glioma, non-small cell lung cancer (NSCLC), acute myeloid leukemia (AML), and acute lymphocytic leukemia (ALL)." (PMID 32587767, 2020). "Our study revealed a co‐expression relationship between MYC and ABCC1 and that the overexpression of MYC up‐regulated ABCC1, indicating that MYC may affect the drug resistance of glioma cells by regulating ABCC1." (PMID 32916774, 2020). "Furthermore, MYC was positively correlated with ATP‐binding cassette subfamily C member 1 (ABCC1) expression in glioma cells and MYC up‐regulated ABCC1 expression." (PMID 32916774, 2020). "ABCB1/P-gp, ABCG2/BCRP, ABCC1/MRP1, ABCC4/MRP4, and ABCC5/MRP5 up-regulation has been observed in glioma cells at the mRNA and/or protein level; moreover, MRP3 de novo protein expression has also been detected in high grade gliomas (detailed below)." (PMID 31878061, 2019). "Thus, ferroptosis induction could be an important therapeutic strategy to reverse drug resistance in gliomas with high NRF2 and ABCC1 expression." (PMID 35803910, 2022). "We could not conclude that LncRNA regulates miR-9-5p/ABCC1 axis and then participates in glioma drug resistance." (PMID 34532283, 2021). "Moreover, the SHH pathway is thought to be activated in primary GBM and glioma cell lines, leading to the overexpression of some drug efflux molecules (e.g., ABCB1, ABCG2 [BCRP], and ABCC1 [MRP1]), and MGMT and BMI1, which may explain its association with therapy-resistance." (PMID 32722427, 2020).
osteosarcoma (17 papers, 2012 to 2025). A usually aggressive malignant bone-forming mesenchymal neoplasm, predominantly affecting adolescents and young adults. "In osteosarcoma cells, ABCC1 was the most relevant transporter associated with drug resistance, along with the ABCB1 transporter." (PMID 31380278, 2019). "In vitro and in vivo studies confirmed that C1GALT1 impacts ABCC1 expression and function, further supporting its role in osteosarcoma chemoresistance." (PMID 39844613, 2025). "A study of an ABCB1/ABCC1 inhibitor found that in osteosarcoma cell lines, the inhibitor was able to revert the ABCB1/ABCC1-mediated resistance against doxorubicin." (PMID 27566582, 2017). "CHA59, Saos-2, and HuO9 were immunoprobed for the expression of cell surface markers (CD133, CD24, CD166, CD326, CD44, ABCB1, ABCC1, ABCG2) previously reported to be associated with TSCs and/or osteosarcoma." (PMID 22870217, 2012). "It had been demonstrated that inhibition of MDR1/ABCB1 or MRP1/ABCC1 in the ABC transporter protein family could reverse doxorubicin resistance in tumor cells including osteosarcoma." (PMID 38420199, 2024). "Four members of ABC family have been shown to contribute to multidrug resistance in osteosarcoma, including MDR1 (also called P-glycoprotein, P-gp or ABCB1), multidrug resistance-associated protein 1 and 2 (MRP1/ABCC1 and MRP2/ABCC2), and breast cancer resistance protein (BCRP/ABCG2)." (PMID 35955749, 2022). "Together, our study demonstrated that lncRNA FENDRR may act as an inhibitory molecule of doxorubicin-resistance through down-regulating the expression of ABCB1 and ABCC1 genes in osteosarcoma cells." (PMID 29069754, 2017). "Fendrr enhances doxorubicin resistance in doxorubicin-resistant and-sensitive human osteosarcoma cells by negatively regulating the post-transcriptional expression of the multidrug resistance-related proteins ABCB1 and ABCC1." (PMID 36719027, 2023). "LncRNA FENDRR was found to sensitize doxorubicin-resistance of osteosarcoma cells through down-regulating ABCB1 and ABCC1." (PMID 30153287, 2018). "We found that lncRNA FENDRR was the most down-regulated lncRNA in the doxorubicin-resistant osteosarcoma cells and possibly acted as a drug-resistance suppressing molecule through inhibiting ABCB1 and ABCC1 expression." (PMID 29069754, 2017). "In addition, we found that FENDRR was mainly located in the cytoplasm and could regulate the drug resistance of osteosarcoma cells by negatively affecting posttranscriptional expression of ABCB1 and ABCC1." (PMID 29069754, 2017). "Although there is currently no strong evidence of their contribution to osteosarcomas treatment, other candidate genes such as DHFR, ABCC1 or ABCG2 should be investigated in future studies with large samples." (PMID 39771563, 2024).
colon carcinoma (15 papers, 2010 to 2026). "HIF-1 elevated the transcription of the gene encoding MRP1 (ABCC1) in response to hypoxia, and the inhibition of HIF-1 by siRNA against HIF-1 significantly reversed this effect in colon cancer." (PMID 36551540, 2022). "The same study revealed that down-regulation of ABCC1 expression by miR-133b increases the sensitivity of colon cancer cells to anti-tumor drugs 5-fluorouracil and vincristine." (PMID 32456134, 2020). "Twist1-mediated promotion of ABCB1 and ABCC1 expression levels plays an important role in the drug resistance of colon cancer cells." (PMID 28881781, 2017). "Previous studies have also shown the modulation of ABCB1 and ABCC1 by PUFAs in colon cancer." (PMID 36979758, 2023). "KDM5c inhibits the multidrug resistance of colon cancer cell lines by down-regulating ABCC1." (PMID 35248043, 2022). "For example, the importance of ABCC1 in colon cancer chemoresistance was demonstrated in the study showing that expression of ABCC1 at the gene and protein level was increased in multidrug resistant colon cancer cell lines in comparison with their sensitive counterpart." (PMID 32456134, 2020). "A previous study has investigated the relationships between ABCG2, ABCC1, and ABCB1 genes in two different colon cancer cell lines (Caco-2 and HT-29)." (PMID 41557172, 2026). "This study aimed to evaluate the potential effects of agmatine on cell viability, migration, invasion, apoptosis, and the expression of the ABCB1, ABCC1, and ABCG2 genes in the Caco-2 colon cancer cell line." (PMID 41557172, 2026). "The increased expression of ATP-binding cassette (ABC) transporter genes such as ABCB1, ABCC1, and ABCG2, as other CSC-related characteristic is involved in regulation of self-renewal and multidrug resistance in ovarian and colon cancer cell lines." (PMID 33849536, 2021). "In summary, our data confirmed that Twist1 plays a vital role in MDR of colon carcinoma by upregulating ABCB1 and ABCC1." (PMID 28881781, 2017). "Our study demonstrated that Twist1 can induce MDR in colon carcinoma by promoting the expression of ABCB1 and ABCC1 in vitro and in vivo." (PMID 28881781, 2017). "In the hydroxycamptothecin (HCPT) resistant cell line SW1116/HCPT from human colon cancer cell line SW1116, ABCG2 is the major factor for multidrug resistance, other than well-studied ABCB1 or ABCC1." (PMID 22870247, 2012). "Consistent with their stem cell properties, real-time reverse transcriptase PCR analyses demonstrate expression of ABCC1 and ABCG2 genes in CD133+ colon cancer tumour spheroid cells." (PMID 20332776, 2010). "Isoliquiritigenin downregulated ABCC1 in Caco-2 colon cancer cells but not in leukemic cells, whereas liquiritigenin increased ABCC1 in both." (PMID 40362377, 2025). "Our findings indicate that the major ABC transporters ABCG2, ABCC1, and ABCB1 are not modulated by agmatine treatment in colon cancer cells and do not mediate resistance to agmatine in Caco-2 tumor cells." (PMID 41557172, 2026).
melanoma (15 papers, 2011 to 2024). A malignant, usually aggressive tumor composed of atypical, neoplastic melanocytes. "Another group tested archival melanoma samples from 134 patients and found out that ABCC1 expression was associated with a more aggressive and invasive level V melanoma with statistically significant association with lymph node metastasis." (PMID 32587767, 2020). "This indicates that drugs, which are substrates of ABCC1, can accumulate easily in skin cells when the patients develop skin cancer such as malignant melanoma, potentially increasing the risk of developing drug-induced skin diseases." (PMID 25505559, 2013). "Our analysis revealed a significantly increased expression of ABCC1 and N-cadherin in metastatic melanoma compared with primary melanoma." (PMID 39123364, 2024). "In the current study, we observed elevated levels of ABCC1 in exosomes from three melanoma cell lines stimulated with GH." (PMID 39123364, 2024). "The GH-treated melanoma cells released exosomes with elevated levels of ABC transporters (ABCC1 and ABCB1), N-cadherin, and MMP2, enhancing drug resistance and migration in the recipient cells." (PMID 39123364, 2024). "In melanoma, the synergistic effect of ABCC1 and glutathione S-transferase M1 can also make tumor cells resistant to vincristine." (PMID 35354376, 2022). "They demonstrated expression of HDAC4, MTOR, PLK2, and ABCC1 to be affected in all melanoma cell lines tested." (PMID 28417283, 2017). "Data presented here demonstrated that, in addition to being active against NSCLC lines that expressed intrinsic MRP1/ABCC1 activity, OA modulated factors involved in apoptosis resistance and inhibited the development of melanoma-induced lung metastasis." (PMID 22174843, 2011). "Our results demonstrate that excess GH upregulates ABC transporters, particularly ABCC1, and ABCB1 in the melanoma-derived exosomes, which in turn, can be transferred to treatment-naïve melanoma cells making them drug resistant." (PMID 39123364, 2024). "In the 9 gene signatures, by qRT-PCR, we found that significant differences in the expression of ABCC1, ACSL4 and ALOX5 between normal skin cell lines and melanoma cell lines." (PMID 35354376, 2022). "Further, we and others have shown a direct effect of GH–GHR action in upregulating expression of ATP-cassette-containing (ABC) multidrug efflux pumps such as ABCB1, ABCC1, ABCC2, and ABCG2 in melanoma as well as in breast cancer." (PMID 31547367, 2019). "It was previously shown that GH action in GHR+ human melanoma cells upregulates while GHR knockdown suppresses the ABC-transporter system, especially ABCB1, ABCB5, ABCB8, ABCC1, ABCC2, ABCG1, and ABCG2 differentially in a drug-dependent manner." (PMID 31547367, 2019). "The expression of four selected genes (MTOR, ABCC1, PLK2 and HDAC4) was validated in nine melanoma cell lines by qPCR." (PMID 28417283, 2017). "PLX4032 and PLX4720 also sensitised two wild-type BRAF melanoma cell lines, IPC-298 and SK-Mel-30 (DSMZ, Braunschweig, Germany), that express ABCB1, ABCC1, and ABCG2 to vincristine and mitoxantrone." (PMID 25300205, 2014). "Here, we investigated the role of the ABC transporters ABCB1, ABCC1, and ABCG2 during melanoma cell resistance acquisition to the V600-mutant BRAF inhibitors PLX4032 (vemurafenib) and PLX4720." (PMID 25300205, 2014). "This is of relevance for the design of next-line therapies for melanomas with acquired PLX4032 resistance since ABC transporters including ABCB1, ABCC1, and ABCG2 confer multi-drug resistance." (PMID 25300205, 2014). "Additionally, we showed that the protein levels of ABCC1, ABCC2, ABCB1, and ABCG2 were elevated in presence of GH treatment in parent melanoma cells (Malme-3M and SK-MEL-28)." (PMID 39123364, 2024).
melanoma (continued). "A query of human tumor transcriptomic data for 471 melanoma patients from The Cancer Genome Atlas (TCGA) dataset revealed a positive correlation of IGF1 and ABCC9, ABCG1, ABCB1, and ABCC4 with GHR expression, and ABCC1 with both GHR and IGF1R expression, supporting our observations." (PMID 35865483, 2022).
neuroblastoma (15 papers, 2015 to 2025). Neuroblastoma (NB) is the most common solid, extracranial childhood tumor. "Expression of ABCC1 has been shown to be significantly increased in neuroblastomas and its overexpression is associated with poor patient survival." (PMID 27171227, 2016). "MDR development in cancer is clinically associated with the overexpression of the efflux transporter P-gp (P-gp, ABCB1) or MRP1 (MRP1, ABCC1) in numerous malignancies, including lung, breast, neuroblastoma, and prostate cancers." (PMID 36064415, 2022). "ABCC1, ABCC3, and ABCC4 have been suggested to be linked with tumor growth and prognosis in neuroblastoma." (PMID 34650973, 2021). "This contrasts with a study investigating the role of these transporters in neuroblastoma, where ABCC4 was more associated with proliferation and ABCC1 with migration." (PMID 33081264, 2020). "ABCC1 mRNA overexpression has been reported in small-cell lung carcinoma, prostate, neuroblastoma, acute lymphoblastic leukemia, breast, and glioblastoma." (PMID 31991926, 2020). "ABCC1 (also known as MRP1) is another ABC transporter that is known to be of clinical relevance in neuroblastoma." (PMID 25749379, 2015). "Studies on neuroblastoma (a rare childhood cancer) have confirmed that both ABCC1 and ABCC4 play an important physiological role in its development, independent of their role in multidrug resistance, affecting cellular proliferation, migration, and differentiation." (PMID 33081264, 2020). "Indeed, in neuroblastoma, elevated levels of ABCC1 has been used as a predictor of a poor response to chemotherapy." (PMID 32587767, 2020). "To understand the involvement of ABC transporters in these vincristine-resistant neuroblastoma cells, we probed the expression levels of two well-characterized ABC transporters, ABCC1 and ABCB1." (PMID 40430358, 2025). "It has been reported that knockdown of ABCC1 and ABCC4 decreases sphere formation efficiency of neuroblastoma cells, suggestive of decreased stemness." (PMID 27171227, 2016). "Interestingly, a compelling study revealed a positive correlation between ABCC1 and MYCN in neuroblastoma patients exhibiting MYCN amplification as well as in neuroblastoma cells engineered to overexpress the protein." (PMID 32718079, 2020).